NLRP14 (NLR family pyrin domain containing 14)
Description:
May be involved in inflammation and spermatogenesis.
Synonyms: NALP14; NOD5; GC-LRR; Nalp-iota; PAN8; CLR11.2
Tractability: PROTAC: ubiquitination databases record sites on it.
Gene: Protein-coding gene on chromosome 11 (7,020,462 to 7,072,055, forward strand). Ensembl gene ENSG00000158077.
Subcellular location: Cytoplasm
Subcellular location (Human Protein Atlas): Cytosol
Gene Ontology:
Biological process: spermatogenesis; regulation of inflammatory response
Cellular component: cytoplasm
Genetic constraint (gnomAD): Loss-of-function variants: 91 observed, 91.85 expected, observed/expected ratio (o/e) 0.99, 90% interval 0.83 to 1.18. The upper end of that interval is the gene's LOEUF score, 1.18, which puts it in group 5 of 6, group 1 being the genes least tolerant of losing a copy. Missense variants: 1,300 observed, 1,253.7 expected, observed/expected ratio (o/e) 1.04, 90% interval 0.99 to 1.09. Synonymous variants: 480 observed, 461.87 expected, observed/expected ratio (o/e) 1.04, 90% interval 0.96 to 1.12.
Homologues: Orthologues: chimpanzee NLRP14 (99% identical), macaque NLRP14 (94% identical), dog NLRP14 (77% identical), rabbit NLRP14 (75% identical), guinea pig NLRP14 (56% identical), mouse Nlrp14 (51% identical), rat Nlrp14 (51% identical). Paralogues in human: NLRP5 (38% identical), NLRP13 (36% identical), NLRP8 (34% identical), NLRP2 (27% identical), NLRP12 (27% identical), NLRP3 (26% identical), NLRP7 (26% identical), NLRP4 (24% identical), NLRP11 (24% identical), NLRP9 (23% identical), NLRP1 (23% identical), NLRC5 (18% identical), and 8 more.
Diseases named in the same sentence as NLRP14 in open-access papers:
NLRP14 is named in the same sentence as 14 diseases in open-access papers, as found by Europe PMC text mining. Sharing a sentence is not in itself a finding about the gene and the disease. The quoted sentences say what the papers report.
female infertility (2 papers, 2009 to 2023). Diminished or absent ability of a female to achieve conception. "For example, the knock-out of mouse Nlrp5 induced female infertility due to a blockage of early embryonic development; and the injection of siRNA against Nlrp14 into fertilized eggs resulted in arrested development of embryos between 1-cell and 8-cell stages." (PMID 19682372, 2009).
prostate carcinoma (2 papers, 2015 to 2020). A carcinoma that arises from epithelial cells of the prostate gland. "NLRP14 is considered an oncogene, and increased expression of NLRP14 is associated with increases in prostate cancer mortality." (PMID 33197890, 2020). "In this study, we constructed a model using a Cox proportional hazards model based on the expression of eight immune-related genes that were associated with prognosis in prostate cancer: EDNRB, ANGPTL2, TNFSF15, TNFRSF10D, EDN2, BMP2, NLRP14, and PLK1." (PMID 33197890, 2020). "In TCGA prostate cancer data, rs12791447 acted as an eQTL for PPFIBP2 and NLRP14, which was consistent with the expression levels of blood-related eQTL results for PPFIBP2." (PMID 26443449, 2015).
B cell lymphoma (1 paper, 2023). "Interestingly, as inflammatory signaling pathways contribute to B cell lymphoma transformation, it is tempting to speculate that NLRP14 might contribute to cancer." (PMID 37627102, 2023).
Infertility (1 paper, 2024). "NLRP14 is a key regulator of the differentiation of primordial germ cell (PGC)-like cells, and NLRP14 knockout causes infertility in mice of both sexes." (PMID 38730334, 2024).
lymphoma (1 paper, 2015). A malignant (clonal) proliferation of B- lymphocytes or T- lymphocytes which involves the lymph nodes, bone marrow and/or extranodal sites. "Several of the recurrently mutated genes have not previously been implicated in human lymphoma, including NLRP5, NLRP14, and GRIFIN." (PMID 26377837, 2015).
myocardial infarction (1 paper, 2015). Gross necrosis of the myocardium, as a result of interruption of the blood supply to the area, as in coronary thrombosis. "For example, miR-1 has been reported to be downregulated in various CVDs including myocardial infarction (MI), and it is predicted to target multiple NLR proteins (NOD1, NLRP14, and NAIP)." (PMID 26491223, 2015).
parasitic infections (1 paper, 2024). "Moreover, the involvement of NLRP14 in host resistance to other parasitic infections is considerably understudied." (PMID 39679172, 2024).
cancer (1 paper, 2023). A tumor composed of atypical neoplastic, often pleomorphic cells that invade other tissues. "The variants identified in FTO, TAS2R, and NLRP14 genes were correlated with lifestyle-related factors for cancer installation, which are expected to be found in cases belonging to the LRLS group who are CRC-free." (PMID 37627102, 2023). "Of 94 germline familial variants identified with predicted functional impact, 37 SNPs/indels were detected in 28 genes, 2 of which (MLH1 and PRH1-TAS2R14) have known association with CRC and 4 others (PPP1R13B, LAMA5, FTO, and NLRP14) have known association with non-CRC cancers." (PMID 37627102, 2023).
infection (1 paper, 2021). The state of being infected such as from the introduction of a foreign agent such as serum, vaccine, antigenic substance or organism. "Interestingly, T. gondii infection upregulated the expression of NLRC4, NLRP4, NLRP8, NLRP10, NLRP11, NLRP13, and NLRP14 mRNAs at both 4 and 8 h post-infection, but NLRP4, NLRP8, NLRP10, and NLRP11 mRNAs were significantly downregulated at 8 h post-infection compared to that at 4 h post-infection." (PMID 33712075, 2021).
NLRP14 also shares sentences with these, for which no sentence is quoted: auto-inflammatory syndrome (1 paper); leukemia (1); melanoma (1); neuroblastoma (1); plague (1).